BRAF (B-Raf proto-oncogene, serine/threonine kinase)
Diseases named in the same sentence as BRAF in open-access papers (continued):
Sharing a sentence is not in itself a finding about the gene and the disease.
melanoma (continued). "Flexible switching between RAF isoforms as a mechanism of resistance to RAF inhibitors may be overcome through co-targeting of MEK and IGF1R or PI3K in BRAF inhibitor-resistant melanoma cells (BRAF inhibitor-SB-590885)." (PMID 25785246, 2015). "In summary our findings suggest that prenylation inhibition may be able to target melanoma cells with mutant NRAS or with mutant BRAF and PTEN." (PMID 25646931, 2015). "However, few studies have assessed these combinations in the setting of intrinsic sensitivity to BRAF or MEK inhibitors in melanoma." (PMID 26137449, 2015). "Taken together, our results suggest that complex I inhibition has potential clinical applications as a single agent in melanoma and also might be efficacious in combination with BRAF inhibitors in the treatment of patients with BRAF mutant melanoma." (PMID 26500770, 2015). "While the cells used in this study were melanoma cells it is plausible that this phenomenon will occur in melanocytes contained within nevi, since these melanocytes primarily contain the oncogenic form of BRAF." (PMID 26091525, 2015). "Thus, HGSC with high MAP3K8 protein levels mimic the pathological situation observed in melanoma, which become resistant to anti-BRAF therapy." (PMID 26456302, 2015). "Next we addressed whether RHOB induction by PLX4032 in BRAF-mutant melanoma cells was related to BRAF inactivation." (PMID 26098773, 2015). "Melanoma cell lines with coexistence of PIK3CA and BRAF mutations were also investigated to evaluate the level of interference with the anti-proliferative effects of the BRAF-mutant inhibitor vemurafenib." (PMID 25627962, 2015). "Our results showed that EGb761 induced varying degrees of apoptosis in melanoma cells, which did not appear to be associated with the mutational status of BRAF." (PMID 25860257, 2015). "HGF promotes resistance to drugs targeting HER2 in breast cancer and BRAF in melanoma cell lines." (PMID 25946048, 2015). "ERBB inhibitors, potentially in combination with RAF inhibitors, may prove useful in the setting of acquired resistance to RAF inhibitors in BRAF V600-mutant melanoma, but acquired resistance to first-line therapy was not a focus of our study." (PMID 26084293, 2015). "According to these results, we speculate that there might be a signaling relationship between the ATF2 and BH3 proteins, which are involved in mitochondria-based apoptosis and BRAF inhibitor resistance in melanoma." (PMID 26462148, 2015). "Also, BAY 87-2243 displayed a strong reduction in tumor growth in two patient-derived BRAF melanoma models (MEXF 276 and MEXF 1732)." (PMID 26500770, 2015). "Preclinical data indicating that pharmacologic inhibition of mutated BRAF enhance the immunogenicity of melanoma without adversely affecting the cellular immune response will also be assessed." (PMID 25709607, 2015). "Furthermore, in vitro screening of new drugs should include cell lines with different BRAF mutant levels, thus more closely representative of BRAF-M% in patients’ melanomas." (PMID 26141748, 2015). "In addition to BRAF, NRAS is mutated in 15–25% of all melanomas, most frequently in exon 1 (G12) and exon 2 (Q61)." (PMID 26426340, 2015). "Thus, DTX3L regulating the FAK/PI3K/AKT pathway is a potential target for melanoma patients who have relapsed after BRAF-targeted therapy." (PMID 26033450, 2015). "Furthermore, the regulation of MITF expression and function is strongly linked to the BRAF/MEK/ERK/MAP‐kinase (MAPK) pathway, which is deregulated in >90% of melanomas and central target of current therapies." (PMID 25818589, 2015). "Overall, these results suggest that the sensitivity of BRAF-mutant melanoma cells to BRAF or MEK inhibitors is at least partly mediated by activation of the PI3K pathway and can be enhanced by combined inhibition of the BRAF/MEK and PI3K/mTOR signaling pathways." (PMID 26137449, 2015).
melanoma (continued). "Epigenetic modifiers may also benefit MAPK inhibitor treatment by killing off slowly cycling melanoma cells which are resistant to BRAF/MEK inhibition." (PMID 26426052, 2015). "Another BRAF inhibitor which is currently under development for BRAF-mutant melanoma is LGX818." (PMID 26171394, 2015). "Because BRAF expression emerged as the strongest biomarker for Stage I melanoma in the discovery phase, we performed both survival and multivariate Cox-regression analyses based on 73 Stage I patients (analysis was not executed in additional patients, because none of the 18 patients died)." (PMID 25784655, 2015). "Using the same set of melanoma tissue microarrays, we found that BRAF expression and MMP2 expression are the best markers for AJCC Stages I and II, respectively, whereas p27 cytoplasm expression is a superior prognostic marker for patients in both Stages III and IV." (PMID 25784655, 2015). "Since the antiproliferative activity of selumetinib and vemurafenib was less pronounced in BRAF-mutant melanoma cell lines that expressed pAKT, we investigated if inhibition of PI3K activity could promote growth inhibition in BRAF-mutant melanoma cell lines." (PMID 26137449, 2015). "BRAF and MMP2 proteins showed a progressive increase from Stage I to Stage IV, whereas Tip60 loss is most pronounced in metastatic melanoma (Stage III and IV) as compared to primary melanomas (Stages I and II)." (PMID 25784655, 2015). "BRAF was previously proposed to be the driver of copy number increase in melanoma." (PMID 26141748, 2015). "Although the combined use of BRAF and MEK inhibition has clearly become a new standard for inhibiting the RAF/MEK/ERK pathway in patients with advanced BRAF mutant melanoma the problem of acquired resistance has become a major stumbling block to obtaining long-term disease control." (PMID 26236691, 2015). "A phase III study evaluated nivolumab versus dacarbazine in previously untreated melanoma without BRAF mutation." (PMID 26305724, 2015). "In addition to causing proliferation impairment and cell death in a variety of BRAF mutant and wild type melanoma cells, BAY 87-2243 also revealed strong anti-tumor activity as a single agent in vivo." (PMID 26500770, 2015). "As a proof of concept, we have demonstrated that our approach predicts the efficacy of Vemurafenib in melanoma samples without knowing the mutation status of BRAF; indeed, the prediction corresponded to presence of V600E gain-of-function mutation." (PMID 26320181, 2015). "The second-generation of RAF inhibitors, specifically targeting the mutated BRAF protein – such as vemurafenib, dabrafenib, and LGX818, potently inhibit MEK phosphorylation and cell growth in BRAF-mutated melanomas, being highly effective in inducing rapid tumor regression among melanoma patients." (PMID 26322273, 2015). "Significant advances in the treatment of melanoma have been made with BRAF-targeted therapy, not only leading to significant but short-lived clinical responses in a portion of patients but also leading to immunostimulatory bystander events, which then subside with the emergence of resistance." (PMID 26605342, 2015). "However, treatment with nanomolar levels of mTOR inhibitor renders these cells as sensitive to MEK inhibition as a melanoma cell line with mutant BRAF." (PMID 25955301, 2015). "This differential effect of ERβ agonists on the growth of the different melanoma cell lines might be related either to the specific oncogenic mutational status (NRAS, BRAF) or to the relative expression of receptor isoforms in each cell line." (PMID 26225426, 2015). "Melanomas arising in visceral organs are less likely to be BRAF or NRAS positive." (PMID 26169921, 2015). "Over the last few years, BRAF has received considerable attention as a result of the success of targeted malignant melanoma therapy, and encouraging preliminary results have emerged from exploratory studies of the use of BRAF inhibitors in patients with BRAF-mutated MM." (PMID 26090869, 2015).
melanoma (continued). "This potentially paves the way for sequential analyses of disease status in patients undergoing BRAF-targeting agents, and may complement or represent an advance over previous efforts at tracking genetic changes in melanoma." (PMID 25807549, 2015). "At present, there are three classes of therapies approved for melanoma, the alkylating agents such as dacarbazine, the targeted therapies such as the selective inhibitor of BRAF V600E, and immunotherapeutic agents including anti-CTLA-4 antibody and more recently anti-PD-1 antibody." (PMID 25872534, 2015). "Multiple pharmacological therapies have been approved for malignant melanoma, including BRAF inhibitors (vemurafenib and dabrafenib), MEK inhibitors (trametinib), mAbs, such as Ipilimumab (mAb anti-CTLA4) and Pembrolizumab (mAb anti-PD1), and the oldest chemotherapy drug (dacarbazine)." (PMID 26370966, 2015). "For example, BRAF V600E has been shown to be a potential target in melanoma and other cancers." (PMID 25855536, 2015). "Recently, the impact of Puma was highlighted in BRAF (V600E) melanoma cell lines." (PMID 25831048, 2015). "Previous studies revealed that the BRAF mutation hyper-activated the MAPK signaling pathway and led to MITF promotion, whereas TGFB1 was reported to be down-regulated in multiple cancers, including melanoma." (PMID 25890285, 2015). "Non-p.V600E mutants constitute a significant portion of BRAF mutations in different tumors: NSCLCs (86 %), melanomas (34 %) and CRCs (23 %)." (PMID 26498038, 2015). "In those treated with the T cell checkpoint inhibitor ipilimumab, approximately 21% of patients survive in the very long term and checkpoint inhibiting PD-1 antibody nivolumab recently demonstrated a 30% increase of 1-year survival rate compared to DTIC in BRAF wild-type advanced melanoma patients." (PMID 25871393, 2015). "Detection of CTCs was achieved in patients with either WT or mutant BRAF melanoma." (PMID 25807549, 2015). "Preclinical data suggest resistance in non-V600E BRAF mutant melanoma cell lines." (PMID 26018876, 2015). "However, several mechanisms of resistance to RAF inhibitors have been proposed, and several combinatorial therapy approaches have already been pursued to improve the outcome of patients with BRAF V600E melanomas treated with BRAF inhibitors." (PMID 26630652, 2015). "Importantly, the majority of melanoma cases demonstrate oncogenic activation of the KIT—NRAS—BRAF—MEK—ERK central axis that is a major regulator of cell differentiation and proliferation." (PMID 25646931, 2015). "Previously, melanoma cells that have acquired resistance to BRAF inhibition were shown to have increased PD-L1 levels which could be decreased by treatment with the MEK inhibitor U0126." (PMID 25844720, 2015). "Furthermore, we show that ectopic cytosolic expression of ATF2 restored sensitivity to vemurafenib in BRAF inhibitor-resistant melanoma cells, suggesting that BRAF inhibitor-resistant cells indeed maintain their addiction to the ATF2 pathway." (PMID 26462148, 2015). "BRAF-M% is heterogeneous and frequently increased in BRAF-mutant melanomas." (PMID 26141748, 2015). "In addition to BRAF, NRAS mutations, mostly affecting codon 61, are found in 10–15% of melanomas and are involved in mutagenic activation of the MAPK pathway." (PMID 26305188, 2015). "Another BRAF inhibitor used for treatment of melanoma is dabrafenib." (PMID 26171394, 2015). "This signalling pathway can be activated directly by deregulated RAS oncogenes (mutated in about 25% of melanomas), or indirectly, for example as a result of PTEN loss (the latter commonly found in BRAF-mutated melanomas, which constitute 50-60% of the cutaneous forms of this disease)." (PMID 26008978, 2015). "Besides the intrinsically resistant clones, some of the surviving drug-sensitive melanoma cells are able to adapt to BRAF inhibition." (PMID 25763355, 2015).
melanoma (continued). "This provided initial evidence that overexpression of Mcl-1 might be responsible for acquired resistance to BRAF inhibitors in melanoma cells." (PMID 26497853, 2015). "A recent study indicated that AT13387 treatment could overcome resistance of melanoma cells to BRAF/MEK inhibitors." (PMID 26452257, 2015). "Since BRAF mutation and concurrent down-regulation (reduced expression or loss of function) of PTEN is common in melanomas, we also quantified PTEN expression in BRAF-mutated melanoma cells following combination treatment." (PMID 26299806, 2015). "Metastatic melanoma patients without BRAF mutation (n = 418) were randomized to nivolumab 3 mg/kg every 2 weeks or dacarbazine 1000 mg/m2 every 3 weeks as first line therapy." (PMID 27508107, 2015). "However, treatment with nanomolar levels of an mTOR inhibitor renders these cells as sensitive to MEK inhibition as melanoma with mutant BRAF." (PMID 25955301, 2015). "Indeed, it has been suggested that the presence of preexisting MEK1P124 mutations is associated with poor response and shorter progression-free survival (PFS) in melanoma patients treated with BRAF inhibitor." (PMID 26105199, 2015). "The aim of this study was to investigate the prevalence and distribution of pathogenetic variants in BRAF, NRAS, and PIK3CA genes among 245 DNA samples from pigmented melanomas of cutaneous origin, defining the fraction of cases harboring coexistent PIK3CA and BRAF or NRAS mutations." (PMID 25627962, 2015). "Interestingly, melanoma cells carrying MEK1T55delinsRT actually proliferated faster when treated with low levels of BRAF or ERK inhibitor, when compared to control treatment (Fig4G)." (PMID 26105199, 2015). "The best-validated targeted drugs in melanoma are the selective BRAF inhibitors vemurafenib (PLX4032, ZelborafTM) and dabrafenib (GSK2118436, TafinlarTM) as well as the LGX818 (Novartis) compound that appears to have the highest affinity for the catalytic domain of the kinase." (PMID 26420268, 2015). "BRAF mutations accompanied by a PIK3CA mutation were observed in 2 of 33 (6.1 %) BRAF-mutated lung cancers, 4 of 34 (12 %) BRAF-mutated CRCs, and 2 of 67 (3.0 %) BRAF-mutated melanomas." (PMID 26498038, 2015). "Given that RHOB depletion determines the cellular response to PLX4032 in BRAF-mutant melanoma cells, we hypothesized that the basal expression of RHOB may predict the response to BRAFi." (PMID 26098773, 2015). "The BRAF mutations are especially found in younger individuals and in those with melanomas that originate on the skin not chronically exposed to the sun." (PMID 26322273, 2015). "Importantly, proliferation arrest derived from constitutive stimulation of MAPK by BRAF is an intrinsic property of melanocytes and melanoma cells and is the pivotal mechanism to stop oncogenic progression in nevi, a type of benign melanocytic tumors." (PMID 26496938, 2015). "The evidence reported here further establishes Aurora B kinase as a therapeutic target in the treatment of both BRAF wild type and V600 mutated melanoma either vemurafenib responsive and no longer responsive melanoma." (PMID 25623468, 2015). "Noticeably, expression of YY1 was relatively higher in four melanoma cell lines without BRAF mutation (WM852, WM1791C, WM8 and WM209) compared with normal human melanocyte cultures." (PMID 26104682, 2015). "The adenoviral probe was found to be highly sensitive (88.7%) and specific (99.9%) for melanoma cells and its efficacy was not affected by BRAF mutation status." (PMID 25807549, 2015). "Our data indicate that BAY 87-2243-mediated complex I inhibition, in addition to its function as a single agent, may have therapeutic benefits in combination treatment with the mutant BRAF inhibitor vemurafenib in melanoma." (PMID 26500770, 2015).
melanoma (continued). "For instance, melanoma and colon cancer patients harboring the same BRAF (V600E) mutation respond differently to BRAF inhibitors because colon cancer cells but not melanoma cells gain feedback activation of EGFR and its signaling pathway." (PMID 26220863, 2015). "Unbalanced BRAF mutations have been previously reported to be frequent in smaller series of melanoma; however quantitative methods were not clearly validated, and correlation with mRNA levels was not established." (PMID 26141748, 2015). "Interestingly, PTEN loss conferred resistance against EGFR inhibitors in colorectal and lung cancer, against herceptin in breast cancer or even BRAF inhibitors in melanoma." (PMID 25646931, 2015). "Although BRAF V600E is most applicable as a biomarker in malignant melanoma, we aimed to extend our methods-comparison to colorectal cancer, where BRAF status may also have important implications." (PMID 25318602, 2015). "MPDL3280A is currently being investigated in combination with dabrafenib, vemurafenib or trametinib in advanced melanoma with or without BRAF mutation." (PMID 26305724, 2015). "In November 2014 the study entitled “A Randomized Phase III Trial of Dabrafenib + Trametinib Followed by Ipilimumab + Nivolumab at Progression versus Ipilimumab + Nivolumab Followed by Dabrafenib + Trametinib at Progression in Patients With Advanced BRAF V600 Mutant Melanoma” was launched." (PMID 26171394, 2015). "Indeed, using laser microdissection followed by mutation specific Snapshot assay, a substantial proportion of individual tumor specimens were found to contain a mixture of BRAF mutant and wild-type melanoma cells." (PMID 25789737, 2015). "Activated PI3K-AKT pathway may contribute to decrease sensitivity to inhibitors of key pathogenetic effectors (mutated BRAF, active NRAS or MEK) in melanoma." (PMID 25627962, 2015). "A general solution for resistance to the RAFi in BRAF-mutated melanoma, in particular, is not yet in sight." (PMID 26284497, 2015). "Nevertheless, the effect of zoledronic acid on melanoma cells in vivo and the dependence of biological response on the BRAF or NRAS oncogenic mutation status have not yet been studied." (PMID 25646931, 2015). "Of particular interest in this study were the more pronounced anti-proliferative effects of MLN8054 and trametinib as compared to the combination of trametinib and dabrafenib, a drug combination recently shown to improve progression free survival in patients with BRAF mutant melanoma." (PMID 26136684, 2015). "Taken together these results suggested that Sema6A promotes survival of BRAF-mutant melanoma cells." (PMID 25576923, 2015). "Nevertheless, we also demonstrated that therapeutic sensitivity might be influenced by the PTEN status of BRAF mutant melanoma cells." (PMID 25646931, 2015). "We propose that interfering with WNT5A signaling will affects PI3K-AKT and the β-catenin-MITF-EGFR axis, which would make Box-5 therapy useful for not only BRAFi-resistant melanomas but also melanomas that do not carry BRAF mutations." (PMID 26393652, 2015). "The following open-label, two-stage, phase II trial with two cohorts in patients with metastatic BRAF-mutant melanoma observed significant clinical activity of trametinib with the most common side effects including skin-related toxicity, peripheral edema, nausea, pruritis, diarrhea, and fatigue." (PMID 25915534, 2015). "Blockage of the UPR induced autophagy limits melanoma resistance to the BRAF inhibitor." (PMID 26622781, 2015). "Hence, BRAF V600E is a marker for companion diagnosis, e.g., Melanoma patients treated with vemurafenib, as well as a marker for aggressive papillary thyroid cancer." (PMID 26258049, 2015). "Melanoma cells with BRAF mutation, through their elevated ERK1/2 signaling, activate NF-κB29, which in turn may lead to the transcription of proteins regulating melanoma progression and metastasis." (PMID 26061820, 2015).